AFP (alpha fetoprotein)
Diseases named in the same sentence as AFP in open-access papers (continued):
Sharing a sentence is not in itself a finding about the gene and the disease.
hepatocellular carcinoma (continued). "Patients with alpha-fetoprotein (AFP)-positive hepatocellular carcinoma (HCC) have aggressive biological behavior and poor prognosis." (PMID 38741163, 2024). "Alpha fetoprotein (AFP) is the most commonly used biomarker in hepatocellular carcinoma, often used for detection, diagnosis, and prognosis." (PMID 39136031, 2024). "β-Sitosterol inhibits hepatocellular carcinoma progression by targeting the complement C5a receptor 1/AFP axis to activate autophagy and suppress cell proliferation and migration." (PMID 39315094, 2024). "The current Practice Guidance by the American Association for the Study of Liver Diseases recommends further diagnostic work-up for hepatocellular carcinoma (HCC) in the presence of a hepatic lesion >1 cm and an increase in alpha-fetoprotein >20 ng/mL in serum." (PMID 38256934, 2024). "Alpha-fetoprotein (AFP) is a major biomarker of hepatocellular carcinoma and is found in low levels in normal tissues, where its expression is difficult to detect." (PMID 39339402, 2024). "It has been shown that the levels of AFP in some individuals with hepatocellular carcinoma are minimal, whereas in others they are quite high." (PMID 39834934, 2024). "Patients with higher AFP (> 20ng/ml) possess higher hepatocellular carcinoma (HCC) incidence rate and worse prognosis, one of the most malignant cancer with high mortality." (PMID 38355447, 2024). "Alpha-fetoprotein (AFP) is commonly produced by hepatocellular carcinoma and yolk sac tumors, while AFP in colorectal cancer (CRC) is a rare association." (PMID 38449931, 2024). "AFP-producing adenocarcinoma is a non-hepatocellular adenocarcinoma that secretes the AFP glycoprotein." (PMID 38817451, 2024). "AFP, the first identified oncoprotein, not only serves as a potent prognostic biomarker in hepatocellular carcinoma screening but also plays a critical role in tumor progression by modulating immunoregulatory pathways." (PMID 39309810, 2024). "AFP is a major plasma glycoprotein and an important tumor marker for related malignancies, such as hepatocellular carcinoma and germ cell tumors." (PMID 39336518, 2024). "Because of typical radiological signs hepatocellular carcinoma was suspected, but the serum level of alpha fetoprotein was within normal limits and liver function was preserved." (PMID 39026968, 2024). "AFP is a commonly used biomarker for the detection of hepatocellular carcinoma and testicular and ovarian tumors." (PMID 39337777, 2024). "Several other conditions can result in AFP elevation, including hepatocellular carcinoma, pancreatic cancer, gastric cancer, colorectal cancer, and bronchial cancer." (PMID 39685906, 2024). "Hepatocellular carcinoma (HCC) surveillance is currently performed using a one-size-fits-all strategy with ultrasound plus AFP (US + AFP)." (PMID 39234558, 2024). "Several retrospective studies have indicated that the baseline serum AFP level and early treatment response of AFP were related to treatment efficacy and prognosis of ICIs for hepatocellular carcinoma patients." (PMID 38408930, 2024). "This tumor type has a unique hepatoid appearance of large polygonal eosinophilic neoplastic cells, similar immunohistochemistry (IHC) to hepatocellular carcinoma, and occasionally with elevated serum alpha fetoprotein (AFP) level." (PMID 37974386, 2024). "Reactivation of AFP production in adults occurs during liver regeneration and hepatic carcinoma genesis." (PMID 38834942, 2024). "In contrast, immunohistochemical staining for hepatocellular carcinoma would typically be positive for arginase 1, gpc3 hepatocytes, and AFP, and for cholangiocellular carcinoma, it would be positive for CK19 and CK8." (PMID 39099991, 2024). "The fact that the AFP-targeted CAR T-cell therapy is ongoing for hepatocellular carcinoma treatment provides the possibility for treating AFP elevated AGC patients with AFP targeting." (PMID 38408930, 2024).
hepatocellular carcinoma (continued). "Studies have shown that GPC3 is a reliable marker for hepatocellular carcinoma, with a sensitivity and specificity exceeding those of the alpha-fetoprotein and hepatocyte paraffin tests." (PMID 38919533, 2024). "It is well known that regular follow-up of HBsAg-positive patients to assess disease progression with the help of AFP tests, liver function tests, and abdominal ultrasound is clinically important for the prevention of cirrhosis and hepatocellular carcinoma." (PMID 39791624, 2024). "In addition, the predictive usefulness of AFP levels, a biomarker that has traditionally been linked to the prognosis of hepatocellular carcinoma (HCC), was examined following immunotherapy." (PMID 38711515, 2024). "Currently, alpha-fetoprotein (AFP) is the only serum biomarker used in the management of hepatocellular carcinoma." (PMID 39200161, 2024). "AFP was discovered in the 1960s and was the first biomarker used in the diagnosis of hepatocellular carcinoma." (PMID 37312022, 2023). "Meanwhile, the activated CD8+ T cells by R848@M2pep-MPsAFP-reprogrammed M2-like macrophages possessed the strongest cytotoxicity against murine hepatocellular carcinoma Hepa1-6 cells which expressed AFP antigen in an effector/target ratio-dependent manner." (PMID 37704614, 2023). "The only tumor biomarker routinely used in the treatment of hepatocellular carcinoma is alpha-fetoprotein (AFP) (HCC)." (PMID 37434213, 2023). "Further analyses indicated that CTC-WBC clusters were associated with larger tumor size (OR = 2.65, 95% CI: 1.58–4.44, P < 0.001) and higher alpha-fetoprotein levels (OR = 2.52, 95% CI: 1.50–4.22, P < 0.001) in hepatocellular carcinoma." (PMID 38087278, 2023). "Hyper-fucosylation correlates with the progression of tumorigenesis, as exemplified by the high level of fucosylated-AFP in hepatocellular carcinoma 28 and core fucosylated PD-1 in lung cancer." (PMID 37928424, 2023). "AFP, an important serological marker for hepatocellular carcinoma, teratoma and other cancers, is mainly expressed in the liver and the yolk sac of the foetus." (PMID 37664042, 2023). "In liver tumors, α-fetoprotein (AFP; a marker for hepatocellular carcinoma), Hep Par1 (Hepatocyte paraffin 1, carbamoyl phosphate synthetase I, a marker protein in mitochondria of hepatocytes), β-catenin, and ki-67 proteins were found to be expressed." (PMID 37247123, 2023). "Convenient and rapid detection of alpha fetoprotein (AFP) is vital for early diagnosis of hepatocellular carcinoma." (PMID 37366993, 2023). "The expression of hepatocellular carcinoma markers, including AFP, Arginase-1, Glypican-3 (GPC-3), SALL4, and Hep-1, provides valuable insights into the correlation with hepatocytes." (PMID 37950062, 2023). "The presence of hepatocellular carcinoma (HCC) and chronic liver disease is often linked to elevated levels of AFP." (PMID 37366982, 2023). "AFP levels in the blood can be measured through a blood test, and elevated levels of AFP along with other imaging technologies can suggest hepatocellular carcinoma." (PMID 37685987, 2023). "At present, the early diagnosis of hepatocellular carcinoma can be performed by serum alpha-fetoprotein (AFP) detection, b-ultrasound and CT scanning, but the misdiagnosis rate is high." (PMID 36855431, 2023). "Reportedly, silencing of AFP can be achieved in the hepatoma cell line HepG2 by reducing BIRC5 (survivin) mRNA expression." (PMID 38202502, 2023). "Screening for hepatocellular carcinoma should be performed every 6 months using US and measurement of serum alpha-fetoprotein in patients with cirrhosis." (PMID 36673066, 2023). "The determination of AFP in saliva has been described in a few studies, so in hepatocellular carcinoma, the level of AFP in saliva was 3552.6 ± 2829.9 ng/L, while the normal concentration was lower (18.1 ± 3.8 ng/L)." (PMID 37367072, 2023).
hepatocellular carcinoma (continued). "AFP levels decrease abruptly after birth and are virtually undetectable in adult, although serum AFP levels are elevated in some patients with hepatocellular carcinoma and it is used as a clinical biomarker for diagnosis in this condition." (PMID 37016369, 2023). "Serum alpha-fetoprotein (AFP) is an important clinical indicator for screening, diagnosis, and prognosis of primary hepatocellular carcinoma (HCC)." (PMID 37700838, 2023). "]; α-fetoprotein (AFP) is an important tumor marker with the best sensitivity and specificity for hepatocellular carcinoma (HCC) diagnosis and monitoring of its therapy [22." (PMID 36708488, 2023). "According to Yuri Semenovich Tatarinov, AFP was first accepted as an antigen unique for human HCC (hepatocellular carcinoma)." (PMID 36979610, 2023). "It has been demonstrated that AFP is particularly useful for predicting how responsive hepatocellular carcinoma patients would be to ICI therapy." (PMID 36941725, 2023). "Alpha-fetoprotein (AFP) is a well-known biomarker for hepatocellular carcinoma, but a problem is that serum AFP levels are increased in patients with liver cirrhosis and chronic hepatitis." (PMID 37108200, 2023). "This work presents the design and the development of an optimized tool, i.e., an optical fiber near‐field enhanced plasmonic resonance immunoprobe, for the detection of the AFP which is a biomarker for the hepatocellular carcinoma." (PMID 36995031, 2023). "In contrast to hepatocellular carcinoma, serum alpha-fetoprotein is only abnormal in less than 5% of patients, with 80% of patients having an elevated CA19-9 as seen in our patients in this study." (PMID 37193465, 2023). "AFP is activated in most patients with hepatocellular carcinoma, which also predicts a poor prognosis in these patients and is also a risk factor for recurrence after treatment." (PMID 37312022, 2023). "AFP (Alpha Fetoprotein) encodes alpha fetoprotein, which is commonly associated with hepatocellular carcinoma in adults, and AFP can promote hepatocellular carcinoma progression by inhibiting the HuR-mediated Fas/FADD apoptotic pathway." (PMID 37919386, 2023). "Alpha-fetoprotein (AFP)-secreting hepatocellular carcinoma (HCC), which accounts for ~75% of HCCs, is more aggressive with a worse prognosis than those without AFP production." (PMID 37336873, 2023). "Early‐stage detection of hepatocellular carcinoma was proposed based on a combination of exosomes with microRNA to overcome the inadequate diagnosis and poor sensitivity of Alpha‐fetoprotein (AFP) and ultrasound screening." (PMID 37752943, 2023). "In the treatment of hepatocellular carcinoma, icaritin can suppress cell growth and promote cell apoptosis via down-regulating alpha-fetoprotein gene expression in hepatocellular carcinoma and inducing anti-tumor immune responses." (PMID 37894651, 2023). "Hepatoid adenocarcinoma, as a special pathological type of gastric cancer, is characteristic by the serum high AFP which is frequently elevated in patients with hepatocellular carcinoma (HCC)." (PMID 36647059, 2023). "Hepatocellular carcinoma is diagnosed using ultrasound and blood-biomarker AFP, which can miss up to 40% of diagnoses, delaying the treatment of these patients." (PMID 37760495, 2023). "Beyond AFP (hepatocellular carcinoma), PSA (prostate cancer), and CA125 (ovarian cancer), which have relatively specific diagnostic value, other tumor markers must be comprehensively analyzed according to other clinical information from patients." (PMID 37646233, 2023). "AFP has been reported to be 52% sensitive to tumors larger than 3 cm in diameter in hepatocellular carcinoma patients, and is the most widely used tumor marker in clinical practice." (PMID 37575092, 2023). "Tumor markers (e.g., alpha-fetoprotein), imaging, and histopathology biopsies are commonly used to diagnose hepatocellular carcinoma in clinical studies." (PMID 37848835, 2023).
hepatocellular carcinoma (continued). "Blood AFP level acts as a diagnostic tool for HCC; thus, this confirms the hepatocellular carcinoma induction in mice mode in this study." (PMID 37160480, 2023). "A hybrid biosensor using both antibodies and aptamers was developed to detect alpha-fetoprotein (AFP), a biomarker for hepatocellular carcinoma." (PMID 37232930, 2023). "Alpha-fetoprotein (AFP) is a glycoprotein typically produced by the fetal liver and yolk sac during fetal life, while in adults, high AFP can indicate ongoing hepatic carcinoma." (PMID 37759583, 2023). "Chen Tian-ke’s team confirmed that AFP promoted the proliferation of hepatocellular carcinoma by inhibiting the HUR-mediated Fas/FADD apoptosis signaling pathway." (PMID 37312022, 2023). "Despite the several biomarkers proposed for hepatocellular carcinoma, AFP is still the most widely used criterion." (PMID 36835517, 2023). "Serum AFP is a reliable marker for determining hepatocellular carcinoma and hepatoid adenocarcinoma." (PMID 37950062, 2023). "Background and Objectives: the early diagnosis of hepatocellular carcinoma (HCC) benefits from the use of alpha-fetoprotein (AFP) together with imaging diagnosis using abdominal ultrasonography, CT, and MRI, leading to improved early detection of HCC." (PMID 36899960, 2023). "Ramucirumab was shown to be effective as a second-line treatment after sorafenib in patients with advanced hepatocellular carcinoma (HCC) with alpha-fetoprotein levels > 400 ng/mL in a worldwide phase 3 trial." (PMID 36906542, 2023). "Alpha-fetoprotein (AFP) is currently recognized as the ideal serum protein marker for diagnosing hepatocellular carcinoma." (PMID 37848835, 2023). "In clinical settings, some cases with hepatocellular carcinoma (HCC) demonstrate negativity in both alpha-fetoprotein (AFP) and des-gamma-carboxyprothrombin (DCP)." (PMID 36672339, 2023). "The turn of the 20th and 21st centuries saw a significant increase in knowledge about the fundamental role of AFP in the neoplastic processes, and in the induction of features of malignance and drug resistance of hepatocellular carcinoma." (PMID 36768863, 2023). "As a positive control, alpha-fetoprotein (AFP), a protein produced by certain types of cancer cells, including hepatocellular carcinoma, was utilized." (PMID 37685987, 2023). "We evaluated the effect of AFP response to locoregional therapy (LRT) on the outcomes of hepatocellular carcinoma patients after living donor liver transplantation." (PMID 36900345, 2023). "For instance, multivariate analysis indicated that C-reactive protein (CRP) and serum alpha-fetoprotein (AFP) at baseline were independent predictors of the prognosis of PD-L1-based therapy in hepatocellular carcinoma (HCC)." (PMID 37268978, 2023). "The 400 ng/mL AFP threshold in serum is more accurate in detecting hepatocellular carcinoma than the 200 ng/mL criterion." (PMID 36835517, 2023). "Cancer cells and overexpression of AFP in the tissues derived from this lesion were indicated by H&E and AFP stanning, indicating that this monkey was a rare case of naturally idiopathic hepatic carcinoma." (PMID 37256321, 2023). "An optical fiber near‐field enhanced plasmonic resonance immunoprobe is developed for the detection of the hepatocellular carcinoma biomarker, i.e., the alpha‐fetoprotein." (PMID 36995031, 2023). "AFP is a widely used biomarker for screening hepatocellular carcinoma, which had a sensitivity and specificity of only 39–64% and 76–91%, respectively." (PMID 38069309, 2023). "Only 50 % of cases with hepatocellular carcinoma in human medicine have increased AFP levels in the blood." (PMID 36495211, 2023). "During the follow-up period, elevated alpha-fetoprotein levels were detected, indicating hepatocellular carcinoma recurrence." (PMID 37868545, 2023). "The aim of this study was to evaluate the effect of the AFP response to LRT on the outcomes of hepatocellular carcinoma patients after living donor liver transplantation (LDLT)." (PMID 36900345, 2023).
hepatocellular carcinoma (continued). "Previous research had shown that except for hepatic carcinoma, various human tumors (such as gastric cancer, colorectal cancer, gallbladder cancer, lung cancer, and ovarian cancer) could also cause elevated serum AFP, of which gastric cancer was the most prevalent." (PMID 36211361, 2022). "Hepatoid type is a subtype of primary AFP‐producing colorectal cancer, which has a striking morphological similarity to hepatocellular carcinoma." (PMID 35285179, 2022). "AFP is a well-known biomarker of hepatocellular carcinoma (HCC) and germ cell tumors In addition, it can often increase in acute or chronic liver injury and regeneration, and rarely in stomach, pancreas, and colon cancers." (PMID 35862314, 2022). "Serum AFP concentrations > 400 ng/ml is considered as reliable for supporting the diagnosis of hepatocellular carcinoma." (PMID 35461226, 2022). "AFP is a crucial regulator of cell proliferation in liver cancer, its expression in the serum of hepatoma-bearing mice was also higher than in the control group, but the presentation was not reduced after CPhGs treatment lasted for 21 days." (PMID 36532852, 2022). "The GALAD and ASAP scores are two well-recognized algorithms to estimate the risk of hepatocellular carcinoma (HCC) based on gender, age, alpha-fetoprotein (AFP), protein induced by vitamin K absence or Antagonist-II (PIVKA-II) and AFP-L3 (included in the GALAD score but not in the ASAP score)." (PMID 36263214, 2022). "Biomarkers are widely used in the diagnosis of different tumors due to their simplicity and efficiency, such as alpha-fetoprotein (AFP) in hepatocellular carcinoma and CA19-9 in pancreatic cancer." (PMID 36033465, 2022). "Hepatoid adenocarcinoma is a tumor with a phenotype resembling that of hepatocellular carcinoma, which secretes alpha-fetoprotein (AFP)." (PMID 36456989, 2022). "One study suggested that AFP promotes the expression of PDL1 and causes immune escape of hepatoma cells." (PMID 35399712, 2022). "The investigation of alpha fetoprotein for usage as a tumor-specific biomarker has been reported, for example in hepatocellular carcinoma in humans." (PMID 36539822, 2022). "The REACH-2 trial demonstrated that ramucirumab improved overall survival compared to placebo in patients with hepatocellular carcinoma and AFP levels of at least 400 ng/ml who had previously been treated with sorafenib." (PMID 36518320, 2022). "Three identical tissue chips,containing liver and normal adjacent tissues from 31 patients with hepatocellular carcinoma, were analyzed to compare the expression levels of AFP, ORM1 and HP." (PMID 36096917, 2022). "Our results indicate that the mALF score has better predictive value for prognosis and shows greater sensitivity for predicting risk of postoperative complications as compared with mALBI or AFP in patients undergoing hepatectomy for hepatocellular carcinoma." (PMID 36358711, 2022). "In that same study, AntiGan reduced alpha-fetoprotein (AFP) and carcinoembryonic antigen (CEA) levels; AFP is a marker for hepatocellular carcinoma and CEA is a marker for gastrointestinal cancer." (PMID 35054489, 2022). "Serum AFP has a sensitivity of 40–60% and specificity of 80–90% for the diagnosis of hepatocellular carcinoma at a cut-off value of 20 ng/ml24." (PMID 36096917, 2022). "In a word, salivary ORM1 as a new biomarker of hepatitis B associated hepatocellular carcinoma, combination of salivary ORM1 and AFP as an improved diagnostic tool for hepatocellular carcinoma." (PMID 36096917, 2022). "Elevated serum AFP is commonly seen in hepatocellular carcinoma, liver inflammation due to cirrhosis or hepatitis, and embryonal tumors." (PMID 36016622, 2022). "The sensitivity and specificity of salivary ORM1 combined with salivary AFP in the diagnosis of hepatocellular carcinoma reached 95% and 74.17%." (PMID 36096917, 2022).